AHSA2P (activator of HSP90 ATPase homolog 2, pseudogene)
Description:
Co-chaperone that stimulates HSP90 ATPase activity.
Synonyms: DKFZp564C236; Hch1; AHA1; formerly AHSA2
Gene: Transcribed unitary pseudogene on chromosome 2 (61,177,539 to 61,186,786, forward strand). Ensembl gene ENSG00000173209.